QDPR (quinoid dihydropteridine reductase)
Description:
Catalyzes the conversion of quinonoid dihydrobiopterin into tetrahydrobiopterin.
Synonyms: DHPR; SDR33C1; PKU2; HDHPR
Tractability: Small molecule: a structure with a bound ligand is known; it has a high-quality binding pocket; it belongs to a druggable protein family. PROTAC: ubiquitination databases record sites on it; its protein half-life has been measured; a small molecule that binds it is known.
Target class: Enzyme; Oxidoreductase
Gene: Protein-coding gene on chromosome 4 (17,460,261 to 17,512,206, reverse strand). Ensembl gene ENSG00000151552.
Subcellular location (Human Protein Atlas): Mitochondria
Pathways (Reactome):
Metabolism: Phenylalanine metabolism
Gene Ontology:
Molecular function: 6,7-dihydropteridine reductase activity; electron transfer activity; NADH binding; NADPH binding
Biological process: amino acid metabolic process; dihydrobiopterin metabolic process; tetrahydrobiopterin biosynthetic process; pteridine-containing compound metabolic process
Cellular component: cytoplasm; extracellular exosome; mitochondrion; cytosol
Genetic constraint (gnomAD): Loss-of-function variants: 23 observed, 33.12 expected, observed/expected ratio (o/e) 0.69, 90% interval 0.5 to 0.98. The upper end of that interval is the gene's LOEUF score, 0.98, which puts it in group 4 of 6, group 1 being the genes least tolerant of losing a copy. Missense variants: 324 observed, 340.57 expected, observed/expected ratio (o/e) 0.95, 90% interval 0.87 to 1.04. Synonymous variants: 124 observed, 128.22 expected, observed/expected ratio (o/e) 0.97, 90% interval 0.83 to 1.12.
Gene-disease validity (ClinGen):
ClinGen rates the evidence that QDPR causes each of these diseases.
dihydropteridine reductase deficiency (autosomal recessive): Definitive.
Homologues: Orthologues: chimpanzee QDPR (98% identical), macaque QDPR (98% identical), rat Qdpr (94% identical), pig QDPR (93% identical), mouse Qdpr (93% identical), guinea pig QDPR (88% identical), rabbit QDPR (83% identical), zebrafish qdprb.1 (70% identical), tropical clawed frog qdpr (69% identical), zebrafish qdpra (69% identical), zebrafish qdprb.2 (61% identical), zebrafish qdprb.4 (61% identical), and 3 more.
Diseases named in the same sentence as QDPR in open-access papers:
QDPR is named in the same sentence as 62 diseases in open-access papers, as found by Europe PMC text mining. Sharing a sentence is not in itself a finding about the gene and the disease. The quoted sentences say what the papers report.
DHPR deficiency (10 papers, 2015 to 2025). "The prevalent pathogenic variant was c.353C > T in exon 4 of the QDPR gene in a homozygous state in all our Irish patients with DHPR deficiency (n = 5)." (PMID 39844797, 2025). "PTPS deficiency (PTPSD) caused by mutations in the PTS gene, is the most common disorder in BH4D, followed by DHPR deficiency (DHPRD) caused by defects in the quinoid dihydropteridine reductase (QDPR) gene." (PMID 36583021, 2022). "The guide RNA (gRNA) was designed to target sequences in the vicinity of the c.243G > A variant in the endogenous PTS gene in PTPS deficiency or the c.176C > A variant in the endogenous QDPR gene in DHPR deficiency." (PMID 27798097, 2016). "Expanding the genes in the targeted next generation dystonia panels including SLC18A2 (VMAT2 deficiency), AADC gene (AADC deficiency), QDPR (DHPR deficiency) and PTS (PTPS deficiency) would preempt the necessity of CSF neurotransmitter metabolite measurements." (PMID 25758715, 2015). "Patients were diagnosed as follows: nine patients affected by PTPS deficiency (and identified PTS variants), two patients affected by Pterin‐four alpha‐carbinolamine dehydratase deficiency (and identified PCBD1 variants) and one patient affected by DHPR deficiency (and identified QDPR variants)." (PMID 36537053, 2023).
Hyperphenylalaninemia (10 papers, 2017 to 2025). "WES analysis has shown that neither of these patients had pathogenic, likely pathogenic, or variants of uncertain significance (VUS) above 50% posterior probability in genes associated with hyperphenylalaninemia (GCH1, PCBD1, PTS, QDPR, SPR and DNAJC12)." (PMID 40473815, 2025). "QDPR mutations provoke hyperphenylalaninemia, (also called atypical phenylchetonuria (PKU), a genetic metabolic disease provoking postnatal cognitive deficit due to the neurotoxic effect of hyperphenylalaninemia; interestingly, PKU could be a comorbid condition of ASD, although with low prevalence." (PMID 28993790, 2017). "When no PAH variants are detected in a child with hyperphenylalaninemia, the genes for the various tetrahydropterin BH4 deficiencies are tested, such as GCH1, PTS, QDPR, and PCBD1." (PMID 38132826, 2023). "QDPR gene is involved in hyperphenylalaninemia and has no direct relationship with glucose metabolism." (PMID 34765142, 2021).
Dystonia (5 papers, 2015 to 2023). An abnormally increased muscular tone that causes fixed abnormal postures. "In comparison to defects in BH4 biosynthesis, patients with inborn variants of QDPR present a higher frequency of severe neurological symptoms, including muscular hypotonia, dystonia, microcephaly, epilepsy and brain atrophy." (PMID 30995231, 2019).
phenylketonuria (4 papers, 2012 to 2022). Phenylketonuria (PKU) is the most common inborn error of amino acid metabolism and is characterized by mild to severe mental disability in untreated patients. "To develop a rapid method for the diagnosis of phenylketonuria (PKU) and tetrahydrobiopterin (BH4) deficiency, we designed a multiplex, PCR-based primer panel to amplify all the exons and flanking regions (50 bp average) of six PKU-associated genes (PAH, PTS, GCH1, QDPR, PCBD1 and GFRP)." (PMID 24705691, 2014).
asthma (2 papers, 2011 to 2021). "The asthma-associated variants at that locus (4p15.31) have been shown to act as eQTL of LCORL in kidney tissue cells, and the quinoid dihydropteridine reductase (QDPR) gene in blood." (PMID 34834492, 2021).
diabetic nephropathy (2 papers, 2022 to 2023). "QDPR may be an important factor in mediating diabetic nephropathy through regulating TGF- TGF 1/ Smad3 signaling and NADPH oxidase." (PMID 35320116, 2022).
melanoma (2 papers, 2022 to 2024). A malignant, usually aggressive tumor composed of atypical, neoplastic melanocytes. "Our functional esiRNA screen identified five candidate translation targets of VARS (that is, HADH, KIF13B, SLC7A5, QDPR and GOLT1B), whose depletion re-sensitizes resistant melanoma cells to MAPK therapy." (PMID 38849541, 2024).
ciliopathies (1 paper, 2025). "While CC2D2A and QDPR are primarily linked to ciliopathies and neurotransmitter metabolism, respectively, their potential roles in ovarian biology warrant exploration, as ciliary dysfunction is increasingly recognized as a driver of POI." (PMID 41185014, 2025).
colon tumors (1 paper, 2023). "Human stage 1 colon tumors exhibited a significant decrease in the expression of quinoid dihydropteridine reductase, a key enzyme involved in recycling tetrahydrobiopterin suggesting a potential mechanism for the reduced tetrahydrobiopterin:dihydrobiopterin ratio in these tumors." (PMID 36998441, 2023).
mental disorder (1 paper, 2025). A disease that has its basis in the disruption of mental process. "We identified four key genes and their downstream pathways, specifically QDPR, DBI, MAX and HP genes, linking the mental disorders and susceptibility to the development of IBD." (PMID 40118833, 2025). "By integrating evidence from multi-omics perspectives, we identified four mental disorder-related genes: QDPR (Tier 1), DBI (Tier 1), MAX (Tier 3) and HP (Tier 3) as prior regulatory genes in the pathogenic pathway of IBD and its subtypes." (PMID 40118833, 2025). "We identified four mental disorder-related genes, i.e., QDPR, DBI, MAX and HP and their downstream pathways that played crucial role in the susceptibility of IBD and UC, suggesting their potential as intervention and therapeutic targets for gut-brain axis diseases in the future." (PMID 40118833, 2025).
ovarian dysfunction (1 paper, 2025). The inability of the ovaries to function. "Within the deleted region, four candidate genes (WFS1, CC2D2A, PROM1, and QDPR) warrant detailed discussion regarding their potential roles in ovarian dysfunction." (PMID 41185014, 2025). "Through analysis of Genecards and OMIM databases, we identified two neurodevelopmental genes DRD5 and WFS1, and four ovarian dysfunction-related genes WFS1, CC2D2A, PROM1, and QDPR, suggesting their roles in the patient’s manifestations." (PMID 41185014, 2025). "Ultimately, 2 overlapping genes, including WFS1 and DRD5, for the neurodevelopment and 4 ovarian dysfunction-related genes, including WFS1, CC2D2A, PROM1 and QDPR, were identified." (PMID 41185014, 2025).
Sepsis (1 paper, 2023). Sepsis is defined as life-threatening organ dysfunction caused by a dysregulated host response to infection. "Survival analyses revealed that sepsis cases with low levels of mRNA of ADRB2, QDPR, SCAP, and TLR4 had worse overall survival." (PMID 38011291, 2023).
tumor (4 papers, 2023 to 2025). "Given the relatively low affinity of mouse and human DHFR for BH2 and these findings with the QDPR knockout mouse, QDPR deficiency may partially account for the reduced BH4:BH2 found in tumor tissues." (PMID 36998441, 2023).
genetic disorder (3 papers, 2014 to 2022). "Dihydropteridine reductase (DHPR) deficiency is a rare autosomal recessive genetic disorder caused by the quinoid dihydropteridine reductase (QDPR) gene mutations." (PMID 36132999, 2022).
neurodegenerative disease (3 papers, 2020 to 2025). A disorder of the central nervous system characterized by gradual and progressive loss of neural tissue and neurologic function. "Additionally, aberrant expression of QDPR in certain neurodegenerative diseases further emphasizes its critical role in neurotransmitter synthesis." (PMID 40353060, 2025).
kidney disease (1 paper, 2022). "Although PLPPR1 and SFXN1 genes have not been reported to be associated with kidney disease, the current study found that PLPPR1 and SFXN1 were significantly positively correlated with QDPR and negatively correlated with HAS2 and MYOF." (PMID 35320116, 2022).
QDPR also shares sentences with these, for which no sentence is quoted: microcephaly (5 papers); deficiencies (4); epilepsy (4); (GTPCH) deficiency (3); Developmental delay (3); metabolic disease (3); movement disorder (3); Brain atrophy (2); cognitive deficit (2); dopa-responsive dystonia (2); Intellectual disability (2); Parkinsonism (2); schizophrenia (2); AADC deficiency (1); AIDS (1); alcohol addiction (1); Alzheimer disease (1); and motor delay (1); arrhythmogenic right ventricular cardiomyopathy (1); Arthritis (1); autism spectrum disorder (1); bipolar disorder (1); cancer (1); Cerebral atrophy (1); Chorea (1); congenital myasthenic syndrome (1); D-2-hydroxyglutaric aciduria (1); dilated cardiomyopathy (1); Dravet syndrome (1); Epileptic seizures (1).
A further 16 diseases each share a sentence with QDPR in 1 paper.